IL10 (interleukin 10)
Diseases named in the same sentence as IL10 in open-access papers (continued):
Sharing a sentence is not in itself a finding about the gene and the disease.
infection (continued). "In the current study, TNF-α, IL-8, and IL-10 showed no clear pattern or increase after infection in the ORFV and CvHV2 infection trials, except for an increase in IL-8 levels at day 10 p.i. in animals infected with CvHV2." (PMID 40533814, 2025). "In contrast, only IL-10 and TNF-α were reported in a study of natural infections in Africa." (PMID 40743218, 2025). "Unlike ERBs, elevated TNF, IL-6 and IL-10 cytokine responses are classical hallmarks of severe filovirus disease in both humans and NHPs following natural exposure or experimental infections." (PMID 41181097, 2025). "In addition, 25–100 mg/kg baicalin attenuated the changes in IL-1β, IL-10, IL-18, TNF-α and IFN-γ mRNA expression compared to that in the infection group (P < 0.01)." (PMID 39075562, 2024). "Infection induced no statistical difference in the production of IL-4 or IL-10 when compared to that in the healthy group (IL-4: p > 0.2547; IL-10: p > 0.4021)." (PMID 39598539, 2024). "Caspase-3, caspase-8, or pan-caspase inhibition did not alter secretion of IFN-α2, IFN-γ, MCP-1, IL-6, IL-10, IL-12p70 or IL-23, as elevated levels of these cytokines were detected in all infection conditions." (PMID 38408992, 2024). "The infection with S. pneumoniae augmented the concentrations of both IFNs (IFN-β and IFN-γ), the inflammatory cytokines IL-6 and IL-12, as well as the immunoregulatory cytokines IL-27 and IL-10 in AMphs cultures." (PMID 39766307, 2024). "The cytokine responses as measured by qRT-PCR of lung tissue showed that IL-1, IL-1R, IL-10, IL-17RA, and the IFN-γ receptor genes were all upregulated in response to all three challenges by day 5 after infection, whereas the other measured cytokines showed less consistent responses." (PMID 38535182, 2024). "Additionally, they quantified an induction of human cytokine production at day one post-infection (including IFN-γ, IL-10, IL-1B, and IL-6)." (PMID 39061322, 2024). "Neither IFNγ nor IL-10 blockade had a substantial impact on the expansion of NK cells or their function after infection." (PMID 38950078, 2024). "In the absence of IL-10, an upsurge of IFN-γ and IL-17 from T cells can causing enhanced neutrophil migration to the infection site and increase host mortality." (PMID 38786139, 2024). "When the piglets were injected with baicalin and probenecid, the IL-1β, IL-10, IL-18, TNF-α and IFN-γ mRNA levels decreased compared to those in the infection group (p < 0.01), which suggested that baicalin and probenecid inhibited cytokine production in piglets infected with G. parasuis." (PMID 39075542, 2024). "Our data on the cytokine levels align with the importance of the Th1 response, as all three vaccine formulations induced low levels of IL-4 and undetectable levels of IL-10, with high levels of IFN-γ, in immunized mice and remained detectable in the surviving mice even 30 days after infection." (PMID 39796100, 2024). "Throughout the infection, we noted that pro-inflammatory factors such as IL-1β and TNF-α consistently increased in both serum and liver tissue, while anti-inflammatory factors like IL-4 and IL-10 showed a continuous decline." (PMID 39749332, 2024). "Irrespective of the CovR/S variant used for infections, all three cell types released comparable levels of IFN-γ, tumor necrosis factor (TNF)-α, MCP-1, IL-6, IL-10, IL-12p70, and IL-23." (PMID 38408992, 2024). "Meanwhile, IL-10 was not induced by infection, and no discernible difference in its expression levels was observed between WT and CCR2-deficient mice." (PMID 39051675, 2024). "Significantly reduced levels of bacteria were detected at the site of infection in the peritoneal cavity (PEC) and in systemic organs in the mice that received vaccine + anti–IL-10 compared with mice administered with the vaccine alone or vaccine + isotype control." (PMID 38973612, 2024).
infection (continued). "Patients who received clarithromycin appeared to experience a less pronounced immune-paralysis effect in response to infection, as evidenced by an improved capacity of circulating PBMCs to produce TNF, a decrease in circulating IL-10 levels, and a decrease in the IL-8 to IL-10 ratio." (PMID 38786135, 2024). "Therefore, we examined the expression of cytokine genes (IL-1β, IL-6, IL-10, TNF-α, and GM-CSF) after infection." (PMID 38903792, 2024). "IL-10-generating Treg cells were found to enhance memory T cell generation after LCMV Armstrong infection, contrasting with decreased memory T cell production in clone-13 infection." (PMID 38672681, 2024). "To further assess the immunological response to infection with and without Lcn2 treatment, we first quantified tissuecombat their antimicro levels of IL-10, an important determinant of S. aureus implant infection outcomes." (PMID 38567642, 2024). "In the current study, the levels of expressed mRNA for the anti-inflammatory IL-10 in the cecum were significantly downregulated following primary and secondary infection with E. tenella when compared to the non-infected chickens." (PMID 38492183, 2024). "CAS, BRI, and BRI + CAS are affecting the BMDMs tumor necrosis factor-alpha (TNF-α) production but did not change the levels of the anti-inflammatory cytokine IL-10 during C. neoformans BMDM infection." (PMID 38916308, 2024). "In L. major infection, CD4+CD25+ TREG cells recruit in dermis and, with or without IL-10 contribution, inhibit effector T cells from eliminating the parasite at the infection site." (PMID 38469319, 2024). "While we noticed a slight increase in IL10 induction after infection in M1 macrophages, overall gene expression suggests that Ng does not reprogram M1 macrophages in M2 during the 8h infection we used in our experimental set-up." (PMID 38808065, 2024). "HuN2021 infection was accompanied by the upregulation of proinflammatory cytokines, such as IL-6, IL-1β, IL-8, TNF-α, and CCL8, as well as the immunomodulatory cytokines IL-10 and IFN-γ, at the mRNA and protein levels." (PMID 39506759, 2024). "There was no notable change in lung TNF, IL-12p70 and IL-10 levels at any time point during infection." (PMID 38198478, 2024). "IL-10 expression in the negative control group without infection (37.83 ± 0.84) showed an increase compared to a negative control group with infection (36.3 ± 1.58), although not significantly (p > 0.05) (Figure-2)." (PMID 39185043, 2024). "Contrary to expectation, no cells were found with a CD4+ Th2 transcriptome profile, not even during the late stage of infection, which is hallmarked by increased plasma concentrations of IL-10." (PMID 38535532, 2024). "Moreover, in the post-infection assays (cells infected and further treated), the mRNA levels of SOCS3, IL-10, and IFN-γ were significantly (p < 0.05) upregulated, whereas STAT1 was downregulated." (PMID 38791551, 2024). "However, an attenuated level of IL-10 could be beneficial in the context of Brucella dissemination in the present study, such as in the case of Acinetobacter baumannii infection in the lungs of the mice where IL-10 protected the mice from the infection and contributed to the bacterial clearance." (PMID 39770737, 2024). "Pretreatment of UPEC-infected murine macrophage RAW264.7 cells with viable AC5 (multiplicity of infection, MOI = 1) for 24 hours enhanced macrophage-killing activity and increased proinflammatory (Nos2, Il6, and Tnfa) and anti-inflammatory (Il10) gene expression." (PMID 39091675, 2024). "Worm antigen and mitogen evoked production of IL-4 and IL-10 by splenocytes from wild-type and Pou2f3-/- mice was not appreciably different, suggesting similar systemic immune reactivity to infection with H. diminuta." (PMID 39083533, 2024). "IL-10 was significantly increased in CC061 mice after MRSA infection, while IL-1β, IL-4, IL-9, IL-18, IL-23, and IL-27 were significantly increased in CC024 mice after infection." (PMID 39178306, 2024).
infection (continued). "Cytokines such as IFN-γ, IL-10, TGF-β, TNF-α, and IL-17, among others, play a crucial role in regulating the expression of chemokines and chemokine receptors on immune cells, ultimately shaping the cellular landscape at the site of infection." (PMID 39587036, 2024). "Although the frequencies of CD4+ T, CD8+ T and B cells did not change 20 h after SA infections, repeat SA infections induced significantly higher expressions of IL-10 as measured by the eGFP+ cells." (PMID 39681568, 2024). "The absence of il-10 has also been reported to exacerbate both innate and adaptive immunity in response to Listeria monocytogenes and plays a role in several other infections." (PMID 39436890, 2024). "On the other hand, the levels of IL-1RA, IL-10, IL-12p70, IL-15, and IL-23 were not significantly different between the cells infected with the two bacterial species throughout the infection periods." (PMID 39042701, 2024). "A limitation of this study is the absence of data on the onset of infection, as well as the performance of more than one measurement of IL-10 to follow the dynamics of the production of this cytokine." (PMID 39770719, 2024). "C57BL/6 mice with an IL-4 deletion were somewhat more resistant to infection than control C57Bl/6 mice, but not as resistant as IL-10 deletion mice or DBA/2 mice." (PMID 38535182, 2024). "The CD25+CD71+CD73- relative numbers among B cells did not significantly vary among infection groups; however, IL-10 levels in supernatants from CpG stimulated cultures significantly correlated with them but not with other Bregs subsets." (PMID 39312581, 2024). "During the 3-day ETEC infection process, the inflammatory response induced in the initial stage of infection stimulated the cells of the small intestine of the piglets to produce more TGF‐β and IL‐10, thereby inhibiting inflammation and promoting intestinal tissue recovery from injury." (PMID 39351242, 2024). "Without infection, the serum IL-6 level is very low, but it increases rapidly and sharply during the early stage of bacterial infection, while IL-10 is a potent anti-inflammatory cytokine that works to prevent inflammatory and autoimmune pathologies." (PMID 39195804, 2024). "We were able to detect a small but distinct and reproducible population of cells liberated from the VACV-infected ear that were GFP+ 5d post-infection of the IL-10-GFP reporter mice, but not of WT mice." (PMID 38543790, 2024). "IL-10 (low dose: 17.65 pg/ml; high dose: 21.35 pg/ml) and TNF (low dose: 253.44 pg/ml; high dose: 296.59 pg/ml), showed comparable concentrations in the serum of mice infected with the low and high infection dose." (PMID 38979428, 2024). "Furthermore, in the post-infection assays (cells infected and post-treated), the relative expression of SOCS3, IL-10, and IFN-γ was significantly upregulated." (PMID 38791551, 2024). "SFTSV can infect macrophages in vivo and cause elevated both pro-inflammatory cytokines (such as IL-6 and IFN-γ) and anti-inflammatory cytokines (such as IL-10) in SFTSV-infected patients, and SFTSV infection of macrophages contributed to macrophage differentiation into the M2 phenotype." (PMID 38916398, 2024). "Additionally, OnCL-K1 exhibits the ability to modulate the levels of inflammatory factors, such as IL-6 and IL-10, as well as chemotactic migration factors, including IL-8 and MIF, in Nile tilapia post-infection with S. agalactiae." (PMID 38473757, 2024). "A combination of B. longum and C. sorokiniana was used to study its effect on the antiviral response in HT-29 by measuring the mRNA levels of IFN-γ, IL-10, SOCS3, STAT1, and STAT2 genes in cells with the combination of B. longum/C. sorokiniana in the pre- and post-infection assays with rotavirus." (PMID 38791551, 2024). "In C57BL/6 mice that heal from a primary infection with L. major, IL-10 is necessary for the long-term parasite persistence, and a sterile cure can be achieved in mice lacking both IL-4 and IL-10." (PMID 38543944, 2024).
infection (continued). "Notably, the pulmonary levels of several cytokines and chemokines exhibited a secondary increase at days 21 or 28 post-infection (MIP-1⍺, MCP-1, IL-7, IL-10, IP-10, IL-2, and GM-CSF)." (PMID 39066335, 2024). "In vitro infection of human PBMCs results in production of TNF, IL-6, IL-10, and IL-1β." (PMID 39229265, 2024). "The qRT-PCR tests of the Tumour Necrosis Factor (TNF) α and IL-10 showed a lower to absent gene expression in all the four types of infection." (PMID 38399810, 2024). "Indeed, compared to HC and IPF patients (which again overall behaved similarly), M-COV1/2 PBMCs secreted, upon infection with live PAO1, less IL-8, MIP-1α, IL-1α, IL-1b, TNF-α, G-CSF, MIP-2α, IL-23 and IL-10." (PMID 38835759, 2024). "The results indicated a significant increase in the mRNA and protein expression levels of the inflammatory cytokines IL-6, IL-10, and TNF-α 48 h after H37Rv-RFP infection compared with levels in the controls (hLO alone, M. tb-infected hLO, and hLO containing hMφs)." (PMID 39052544, 2024). "Whole-kidney levels of other neutrophil-recruiting (IL-3, GM-CSF) or inhibitory cytokines (IL-4, IL-10) were not significantly altered by androgen exposure at measured time points after infection (data not shown)." (PMID 38206009, 2024). "In the triple-depletion model presented here, we found that treatment with M-T807R1/Clodrosome prior to infection resulted in an augmented inflammatory signature, as indicated by increased plasma IL-1β, IFN-γ, IL-10, IL-6, and IL-18 levels in the WT-infected animals." (PMID 38668247, 2024). "At 24 h post-ex vivo infection, the median percentage differences in cytokine levels were as follows: IL-2 and IL-4 both showed no change at 0%; IL-10 exhibited a significant increase at 104%; TNF-α at 167%; and IFN-γ at 197%." (PMID 39456722, 2024). "The administration of HEBP significantly influenced IL-10 expression in both the treatment groups without infection and the treatment groups with infection (p = 0.0006)." (PMID 39185043, 2024). "Based on this observation, we cannot rule out that MDSCs infiltrate the spleen during infection and promote the differentiation of Treg cells as a source of IL-10, as has been previously reported." (PMID 39529636, 2024). "WT and HuR KO RAW264.7 cells were infected with 1 MOI HAZV and at 9 h post infection, the expression of Il6, Ifnb, Tnf, Cxcl10, Il10, Il12p40, Ccl2 and Tgfb relative to non-infected control cells and the copy number of S segment inside cells were measured." (PMID 39348382, 2024). "This activation leads to B cell activation and antibody production, primarily influenced by post-infection neutrophils, and is independent of Interleukin-10 (IL-10)." (PMID 39697335, 2024). "The authors showed that while IL-10 levels decreased, IFN-γ and TNF-α levels increased, diminishing the IL-10 production rate relative to the other two cytokines, thus favoring a pro-inflammatory effect at the late stage of infection." (PMID 38787228, 2024). "Furthermore, we observed a significant increase in TNFα, IL-1α, IL-2, IL-3, IL-4, IL-9, IL-10, IL-12 (P70), IL-17A, and CCL5 on day 4 post-infection in murine macrophages." (PMID 39038037, 2024). "The inflammatory cytokines TNFα, IL-4, IL-6, IL-13, IL-10, IL-12 (P40), and IL-12 (P70) along with chemokines including CCL2, CCL3, and CCL5, were significantly elevated in the plasma of c-Flip+/–mice on day 2 post-infection compared that of WT mice." (PMID 39038037, 2024). "Although there was no significant change in IL-10, it showed an upward trend after infection which was reduced by GCTA, consistent with previous results." (PMID 38715123, 2024). "Furthermore, the study examined the levels of IL-6, IL-10, IL-8, and MIF gene expression in different tissues and organs following artificial infection of tilapia, as well as the extent of tissue damage." (PMID 38473757, 2024). "However, after 8 weeks of infection, TLR2KO mice presented a reduced frequency of IL-10+ PMN-MDSCs compared to WT mice." (PMID 39035356, 2024).
infection (continued). "In the negative control group with infection, the expression levels of IL-10 and IL-4 were lower than those in the negative control group without infection and with no bacteria." (PMID 39185043, 2024). "We did not detect differences in liver IL-1β or IL-10 levels after infection, suggesting that local inflammation alone is not readily equated with the end-organ tissue damage observed." (PMID 37788087, 2023). "Infection with C. difficile alone (P) resulted in a significant increase in proinflammatory cytokines, although we were not able to detect IL-10." (PMID 37108065, 2023). "Genes such as TNFα, IL10, TLR15, IL8L1 (CXCLi1), IL8L2 (CXCLi2), NOS2, ACOD1 and PTGS2 were upregulated with infection and microbiota, suggesting that macrophages may largely participate in the pro-inflammatory response described in caecal tissues." (PMID 38098020, 2023). "Conversely, when each infection subgroup was separately analyzed (PI, HC, R and NI), IL-10 showed a negative correlation between compartments (r = −0.6598; p = 0.0272, Pearson) only in R patients." (PMID 37896882, 2023). "In human macrophages, we observed that the infection induced a strong upregulation of TNFα and a slight upregulation of IL-10 at 4 h post-infection independent of the availability of oxygen." (PMID 36793725, 2023). "The levels of IL-6, IL-10 and IL-12p70 were low and not significantly different in BM supernatants during and after the infection." (PMID 37539049, 2023). "The colonic cytokine contents were analyzed, and it was detected that CR infection promoted the pro-inflammatory factors IL-1β, TNF-α, IL-6, and IL-17A (p < 0.01), as well as the anti-inflammatory factors IL-4 (p > 0.05) and IL-10 (p < 0.01)." (PMID 37111225, 2023). "In the present study, expression of inflammatory cytokines (IL-1 β, IL-6, IL-10, TNF α and iNOS) and acute phase protein SAA were up-regulated post infection, especially that of the vaccines immunized groups, indicating that vaccination promoted host innate immunity of M. amblycephala." (PMID 36969197, 2023). "Simultaneously, IL-10 treatment in the late stage of infection effectively mitigated the production of pro-inflammatory factors such as IL-6, INF-γ, and TNF-α at 72 h post-infection, which are consequences of the inflammatory response." (PMID 38035330, 2023). "The observed increase in Th2 and Th IL-10+ cells following antibiotic treatment, which occurred irrespective of infection status, is also notable." (PMID 37898618, 2023). "Cangma Huadu granules increased the abundance of Bifidobacterium, Parasutterella, Bacteroides, and Faecalibaculum in the intestine of mice at 7 days of PR8 infection, decreased the viral load and lung damage in the lungs, decreased TNF-a and IL-1β levels, and increased IL-10 levels." (PMID 37928517, 2023). "We showed that depletion of Treg cells prior to infection of C57BL/6 mice not only increased pathology in the tibiotarsal joints but also created an environment in which restimulated cells produced more IFN-γ and less IL-10." (PMID 36839461, 2023). "We have shown that the individuals who cleared the infection due to MDA had the lowest IL-10 and Tregs levels when compared to both the latent and patent patients, suggesting that IL-10 might serve as a signature for MF release or ongoing filarial infection." (PMID 37242335, 2023). "Moreover, DMI markedly suppressed IL-6 and IL-10 production in BMDMs infected with Mtb, BCG, or Mav, compared with those induced by the infection alone." (PMID 36882813, 2023). "In the present study, IL-10 levels, regardless of the presence of the infection group, were similar between groups." (PMID 37239991, 2023). "However, in the case of prolonged infections, the percentage of CD4+CD25+Foxp3+ Treg cells and serum levels of TGF-β and IL-10 were also found to be increased." (PMID 36985175, 2023).